AMH (anti-Mullerian hormone)
Diseases named in the same sentence as AMH in open-access papers (continued):
Sharing a sentence is not in itself a finding about the gene and the disease.
Infertility (continued). "Confounding variables such as age, body mass index, infertility duration, previous IVF attempts, types of infertility, basal FSH, AFC, and AMH were included in the analysis." (PMID 31803144, 2019). "Our results propose that regarding number of oocytes retrieved, AMH is a better predictor in comparison to age, BMI, AFC and FSH, particularly in younger infertile population (20 to 35 years)." (PMID 27648045, 2016). "Few studies have assessed the levels of FSH and AMH at various ages in infertile women, therefore our aim was to investigate the changes in serum concentrations of AMH and FSH at different ages and its correlation with ovarian reserves in infertile women." (PMID 25918589, 2015). "We intended to establish the threshold of Anti-Mullerian Hormone (AMH) for detection of Ovarian Hyper-Stimulation Syndrome (OHSS) and poor response to treatment in Iranian infertile women." (PMID 26357853, 2015). "Assessments of AMH and FSH levelsin combination with female age can help in predicting ovarian reserve in infertile women." (PMID 25918589, 2015). "This cross-sectional study analyzed serum AMH and FSH levels from 197 infertile women and 176 healthy controls, whose mean ages were 19-47years." (PMID 25918589, 2015). "However, after adjustment for age, BMI, AMH, ICSI, infertility diagnosis, stimulation protocol, total gonadotropin dose, oocytes retrieved, mature oocytes, and fertilized oocytes, this difference became non-significant (adjusted RR = 1.06, 95% CI: 0.99–1.13)." (PMID 41607608, 2026). "Backgrounds: Evaluating the AMH level and AFC are crucial in infertility practice." (PMID 40141728, 2025). "In RF models, the majority of the top features are shared, including age (years), paternal age (years), embryo score of the 1st embryo, LH (IU/L), AMH (pmol/L), TSH (mIU/L), FSH (IU/L), BMI (kg/m2), day of the transfer, number of follicles and duration of infertility (years)." (PMID 40648778, 2025). "In addition to AMH and AFC, the second study also reported outcomes such as menstrual irregularities, primary vs. secondary infertility, Follicle-stimulating hormone (FSH), luteinizing hormone (LH), and Estradiol concentration." (PMID 41358262, 2025). "The quality of life among women treated for infertility did not correlate with age, place of residence, BMI, time trying to have a baby, income, LH, AMH, or TSH levels (p > 0.05)." (PMID 39941391, 2025). "Both models share AMH and TSH in the top five features, and share FSH, LH, duration of infertility, the three endometrial data, embryo scores of the first and second embryo, sperm concentration and motility, and maternal and paternal age in the top 15 features." (PMID 40648778, 2025). "First-line surgery has recently been linked to improved pregnancy and livebirth rates compared to first-line IVF in infertile patients with DE without bowel involvement and low AMH (<2 ng/mL)." (PMID 40507534, 2025). "In addition to lifestyle influences, hormonal abnormalities, such as altered levels of follicle-stimulating hormone (FSH), luteinizing hormone (LH), testosterone, anti-Müllerian hormone (AMH), and prolactin, are frequently observed in men with infertility." (PMID 41048990, 2025). "Two other patients with FA have married since the date of AMH testing, but neither have children with one reporting infertility on evaluation by specialists." (PMID 39032500, 2024). "The differences in patients’ age, the proportion of infertility factors, infertility duration (years), BMI, AMH, basic FSH value and other indicators among groups were not statistically significant (p>0.05." (PMID 39554641, 2024). "The estimated centiles for AMH and AFC for the fertile and infertile groups were generated." (PMID 39446778, 2024).
Infertility (continued). "The negative correlation between FSH and AMH is not unexpected in infertile women undergoing IVF treatment, as it had already been documented in the literature, although with a significantly smaller sample size (n=81) compared to our study (n=537)." (PMID 38737557, 2024). "It was shown that the vitamin D levels of female patients who came to our clinic because they were infertile did not significantly correlate with the markers of ovarian reserve, particularly AMH, FSH, and AFC." (PMID 39554321, 2024). "A previous large study has also established a clear positive correlation between AMH and testosterone levels in infertile women without PCOS." (PMID 39336427, 2024). "Age cut off for decline in AMH and AFC in infertile women was found approximately 34 years." (PMID 39446778, 2024). "According to Kruskal-Wallis test, there were statistically significant differences in age, BMI, infertility type, AMH and AFC among all groups, with age and BMI higher in group E2 than those in other groups (P < 0.05) but AMH and AFC lower in group E2 (P < 0.001)." (PMID 37612626, 2023). "In non-PCOS women seeking infertility treatment, high stress levels did not correlate with AMH levels." (PMID 37170133, 2023). "After postmatching analysis, the baseline characteristics, including maternal age, paternal age, BMI, duration of infertility, type of infertility, indication for IVF/ICSI, basal serum FSH level, AMH and AFC, were comparable between the mild stimulation and conventional stimulation groups." (PMID 38033995, 2023). "AMH of < 1 ng/mL is an independent predictor of increased miscarriage rate in patients with non-PCOS infertility undergoing ART without pre-implantation genetic testing." (PMID 37020210, 2023). "This study shows that low serum AMH is a marker for poor gonadal function illustrated by impaired semen quality and lower serum inhibin B, inhibin B/FSH ratio, testosterone/LH ratio, and higher serum FSH in a well-characterized cohort of infertile men." (PMID 36855109, 2023). "AMH, basal follicle-stimulating hormone (FSH), basal LH, and T levels were significantly lower in the OW+IR group compared to those in the NOW+NIR group, whereas the number of years of infertility was significantly higher." (PMID 37554761, 2023). "The baseline characteristics of the non-PCOS infertility patients were notable for having a lower mean AMH of 2.8 ng/ml compared to 6.1 ng/ml in the patients with PCOS." (PMID 37020210, 2023). "Our study investigated whether there was an association between TSH values and ovarian reserve markers such as AMH, FSH, and AFC in a population of 1443 infertile women." (PMID 37925426, 2023). "Among infertility patients with endometriosis, with and without a history of ovarian surgery, ovarian reserve markers were worse (lower AMH and higher FSH)." (PMID 37959232, 2023). "Public education about the lack of utility of AMH testing for women not undergoing infertility treatment is also needed to prevent women undergoing testing in the belief that it can provide reliable insights into their fertility and reproductive timeline." (PMID 37603332, 2023). "Other studies attempted to remove PCOS related infertility patients based on AMH levels > 6 ng/ml, which likely did not adequately exclude all PCOS patients." (PMID 37020210, 2023). "AMH < 1 ng/mL is an independent predictor of increased miscarriage rate in patients with non-PCOS infertility." (PMID 37020210, 2023). "Due to the high level of AMH in the patients with PCOS and the possibility of developing ovarian hyperstimulation during infertility treatment in these patients, we decided to compare the level of AMH before and after Laparoscopic Ovarian Drilling (LOD) in these patients and its effect on fertility." (PMID 36042475, 2022). "Factors considered as inclusion criteria, including age, BMI, infertility cause, baseline FSH and AMH level, were not different, while the serum estradiol level was different." (PMID 35222266, 2022).
Infertility (continued). "Very high AMH or AFC is not necessarily good; women with polycystic ovarian syndrome can have high AMH levels or AFC and are at risk for infertility through anovulatory cycles, not a lack of oocytes." (PMID 35566443, 2022). "The analysis of a model by using all related factors (i.e., full model) showed that including BMI, AMH, duration of infertility, endometrial pattern and VI did not improve prediction." (PMID 35941542, 2022). "Results also demonstrate that, with the increase of AFC, AMH, days of Gn, Dosage of Gn, and E2 level on the HCG day, the general number of oocytes retrieved would also increase; the increase of age, infertility duration, and bFSH would, however, reduce the number of oocytes retrieved in return." (PMID 35204580, 2022). "Univariate analysis showed that the predictive factors for the success of the OPTIMUM treatment strategy were younger age (OR = 1.25, 95% CI = 1.11–1.41), high AMH level (OR = 0.65, 95% CI = 0.44–0.95), and no infertility (OR = 3.84, 95% CI = 1.41–10.45)." (PMID 34646081, 2021). "We found that AFC, serum AMH levels, and ORPI were stable and reliable in both the fertile and infertile groups, and could more accurately reflect the ovarian reserve." (PMID 33907092, 2021). "We looked at patients in Poseidon group 3 (age<35 and AMH <1.2 ng/mL) who had no other known reasons for infertility." (PMID 34925238, 2021). "Different studies have calculated various AMH cut-offvalues for hyper-response in non-PCOS infertile womenand in patients with PCOS." (PMID 33687164, 2021). "After postmatching analysis, the baseline characteristics, including maternal age, paternal age, BMI, duration of infertility, type of infertility, indication for IVF/ICSI, basal serum FSH level, basal serum LH, AMH and AFC, were comparable between the hMG +DYG group and hMG +MPA group." (PMID 34630325, 2021). "Differences in age, pregnancy history, anti‐Müllerian hormone (AMH) levels, prevalence of infertility, and pregnancy procedures were not significant in both groups." (PMID 34646081, 2021). "A previous study reported that AMH is a better clinical predictor of cycle success in COS IVF cycles, although FSH, antral follicle count, and AMH are widely used to assess the ovarian reserve in women undergoing infertility evaluation." (PMID 33246461, 2020). "In women without a history of infertility, the AMH level is used to assess the ovarian reserve, or the number of functional oocytes; a high level can be associated with cycle irregularities." (PMID 32326591, 2020). "In our study of infertile patients (idiopathic infertility), we found no AMH influence on embryo quality." (PMID 31885768, 2019). "In another study among 23 pairs of infertile and fertile women, it was found that both TSH levels and age were negatively correlated with AMH levels in infertile participants with standardized partial regression coefficient (β) of − 0.534 and − 0.361, respectively, but not in normal fertile ones." (PMID 31064360, 2019). "The present study revealed that the AMH was fair but not a powerful predictor of clinical pregnancy and live birth in TF infertility women." (PMID 30288481, 2018). "The age, infertility duration, and baseline hormone profiles (FSH, LH, E2, and AMH) did not significantly differ between the CA and daily rFSH groups in the patients with low, moderate, and high AMH levels." (PMID 30427868, 2018). "This study demonstrated that 50,000 IU vitamin D supplementation every other week for 8 weeks resulted in significant decreases in serum AMH, insulin levels and HOMA-IR score, and a significant increase in QUICKI in infertile women with PCOS who were candidate for IVF." (PMID 30286768, 2018). "Patient AMH, BMI, number of embryos transferred, stimulation protocol type, infertility factors, or previous IVF attempts did not influence clinical pregnancy and/or live birth chance significantly or independently." (PMID 29445356, 2018).
Infertility (continued). "Adoption of AMH and AFC criteria by NICE was proposed for screening women with infertility and menstrual irregularities and encouraging adoption of AFC for those presenting with menstrual irregularities was the best choice to generate data for screening policy." (PMID 29201666, 2017). "In this study, we will examine AMH levels in infertile women, assess their stress through SAA and analyze whether psychological stress is related to serum AMH level in infertile women." (PMID 28693593, 2017). "Anti Mullerian hormone (AMH) is gaining place as ovarian marker, chiefly in infertility assistance." (PMID 27648045, 2016). "Measuring AMH levels in combination with AFC may improve the assessment of ovarian reserve for evaluating fertility potential and monitoring infertility treatment." (PMID 25780521, 2015). "In this study infertile women had higher FSH levels and lower AMH levels than fertile women." (PMID 25918589, 2015). "In addition, AMH was assessed in the different treatment groups because FSH and E2 measurements cannot express the ovarian reserve before infertility develops." (PMID 26465611, 2015). "Among 158 consecutive cycling infertility patients (none of whom carried the premutation) under age 40 at a single center in the US, AMH was lower in women with 35–50 CGG repeats (n = 35) than in women with <35 repeats (n = 122, p = 0.025)." (PMID 25071825, 2014). "Conversely, AMH expression is negative in the control groups, further supporting a role of hAFC transplantation in restoring ovarian function in infertile mice." (PMID 24006896, 2013). "Uniformly lower levels than in infertile women suggest that AMH levels do not appear as stable under all hormonal influences as previously reported." (PMID 21777422, 2011). "The four subgroups, formed on the basis of the AMH level, did not significantly differ for age, BMI, and infertility duration." (PMID 21824441, 2011). "In a multivariable logistic regression analysis adjusted for arcuate uterus, BMI, anti‐Müllerian hormone (AMH), ovulatory disorder, and male factor infertility, the presence of an arcuate uterus was not independently associated with live birth (aOR 1.3, 95% CI 0.2–5.9, p = 0.82)." (PMID 41458291, 2026). "Moreover, the American College of Obstetricians and Gynecologists (ACOG) does not currently recommend the use of AMH for fertility counseling in women without infertility diagnoses." (PMID 40941763, 2025). "Except for the number of antral follicle (14.21 ± 6.60 vs. 16.04 ± 5.82, P = 0.001) and AMH (3.93 ± 3.14 vs. 4.53 ± 3.42, P = 0.043), none of the maternal-related parameters such as BMI, infertility year, E2 and progesterone levels on trigger day showed a marked difference between two groups." (PMID 38650716, 2024). "Furthermore, thyroid health, both in terms of TSH levels and the presence of thyroiditis, does not significantly affect AMH when infertile patients are euthyroid." (PMID 39336427, 2024). "Serum AMH in infertile men was not influenced by vitamin D supplementation." (PMID 36855109, 2023). "The elevated AMH associated with PCOS may have skewed the data; removing this sub-population may have unmasked significance within the non-PCOS associated infertility." (PMID 37020210, 2023). "In people without a diagnosis of infertility, AMH is a poor predictor of spontaneous pregnancy." (PMID 35566443, 2022). "This could be a novel finding of our study that AMH has a strong positive correlation with cumulative live‐births in couples with true unexplained infertility but not in other etiological categories, but it requires further validation." (PMID 33850452, 2021). "Some researchers believe that active treatment could be considered for young women with extremely low AMH levels, except for those with low AMH levels but no infertility factors." (PMID 34721287, 2021). "However, the PPV in young women is poor, and AMH does not appear to predict time to pregnancy in non-infertile women." (PMID 32404103, 2020).
Infertility (continued). "In conclusion, we showed in a cohort of women affected by infertility that chemerin and omentin expression in FF and GCs is electively increased in the PCOS group, while ECHO women are characterized by high levels of adiponectin, apelin, and APJ, as well as lower plasma AMH and LH levels." (PMID 31382403, 2019). "Therefore, this study was conducted to determine the effects of vitamin D supplementation on the levels of anti-Müllerian hormone (AMH), metabolic profiles, and gene expression of insulin and lipid metabolism in infertile women with PCOS who were candidate for in vitro fertilization (IVF)." (PMID 30286768, 2018). "Indeed, we found that circulating AMH levels and AMH/tT values allowed dichotomizing a homogenous cohort of white-Caucasian primary infertile men with iNOA into positive vs. negative sperm retrievals at microdissection testicular surgery, with >93% accuracy." (PMID 29247212, 2017). "Since serum AMH level is not dependent on the phases of the menstrual cycle, measurement of serum AMH levels has become part of routine clinical practice even outside of infertility treatments." (PMID 27793163, 2016). "Very low serum AMH level on biochemistry implies further surgical intervention may not be the first choice for an infertile endometriosis patient, under the consideration of insufficient ovarian reserve." (PMID 26359251, 2015). "However, most data about AMH and PCOS are from western countries, and on infertile adults." (PMID 28913069, 2015). "Although AMH may have a higher predictive value for evaluation of ovarian reserve, early follicular phase FSH level is commonly used in routine clinical evaluation of the infertile women." (PMID 25083178, 2014). "First, we did not stratify study subjects by infertility aetiology, although evidence suggests that different types of reproductive pathology might impact serum AMH in different ways." (PMID 22136508, 2011). "This inconsistency may be due to the inclusion of patients with PCOS related infertility in prior studies as the association of PCOS with abnormally elevated AMH may mask an association between low AMH levels and the probability of miscarriage in non-PCOS women with infertility." (PMID 37020210, 2023). "Besides, AMH was assessed in the various treatment groups because the evaluations of FSH and E2 could not express the capacity of the ovary to provide egg cells and fertilization before infertility development." (PMID 34889997, 2021). "Therefore, gynaecologists should not overlook the decrease of AMH levels after unilateral and bilateral laparoscopic endometrial surgeries, since the decreased ovarian reserve may result in infertility, or premature menopause in future." (PMID 32972380, 2020). "The binary logistic regression revealed no impact of TSH levels on the implantation rate, clinical pregnancy rate, miscarriage rate, and live birth rate whether confounders such as female age, final IUI scheme, BMI, infertility duration, and serum AMH levels were adjusted or not." (PMID 31933640, 2019). "The differences in BMI, male age, duration of infertility, the number of prior failed transfer, IVF indication and AMH between the two groups were not statistically significant (p>0.05)." (PMID 41244041, 2025). "Age, BMI, history of adverse pregnancy, Infertility years history of assisted reproduction, FSH, E2, AMH, PRL, P, number of eggs harvested were not significantly different between the two groups." (PMID 38053145, 2023). "No statistical differences were found in age, years of infertility, BMI, basal serum FSH, basal serum E2, AMH, and AFC between the two groups." (PMID 37165315, 2023). "Both AMH and age-based counseling should be considered when discussing the probability of clinical success for women without PCOS related infertility when undergoing ART." (PMID 37020210, 2023).